FZD8 (frizzled class receptor 8)
Diseases named in the same sentence as FZD8 in open-access papers (continued):
Sharing a sentence is not in itself a finding about the gene and the disease.
tumor (32 papers, 2012 to 2025). "It has been reported that FZD8 was robustly upregulated in bone-metastatic PCa cell lines and tissues, and FZD8 upregulation was significantly positively associated with clinical tumor progression and bone metastasis." (PMID 32182839, 2020). "In BPH, a strong reaction was demonstrated showing β-catenin and Fzd8, especially in the membrane of glandular epithelial cells of the prostate, while in the tumor sections, a positive reaction was found in the nuclei of some cells." (PMID 41465498, 2025). "Prior studies indicated that FZD8 is overexpressed in diverse tumours, resulting in bone metastasis and resistance to treatment by activating the canonical Wnt/β‐catenin pathway." (PMID 37771187, 2023). "Current study identifies that malignant cells in SCLC have inter‐patient and intra‐tumor heterogeneity, high expression of genes such as FZD8 in WNT pathway is associated with drug resistance, and SCLC harbors a unique immunosuppressive tumor microenvironment." (PMID 36618022, 2022). "On the contrary, FZD8 mRNA levels were elevated in PTC tissues compared to the matched non-tumor tissues." (PMID 35859793, 2022). "FZD8 was investigated as a potential drug target to inhibit HNSCC stem-like cells in order to block tumor formation." (PMID 34604862, 2021). "This revealed significantly higher levels of FZD8 and Wnt-11 in tumor cells, compared to in benign epithelium and correlations in the levels of FZD8 and Wnt-11 in benign and tumor epithelia and stroma." (PMID 29717114, 2018). "We found that tumor weight of FZD8 knocking-down treated groups was significantly less than that of the control treated group (P<0.001)." (PMID 29108281, 2017). "We observed that knocking down FZD8 expression in the two cell lines not only inhibited proliferation in vitro, but also suppressed tumor growth in vivo." (PMID 29108281, 2017). "The immunohistochemical analysis showed high expression of FZD8 in RCC tissues compared with peri-tumor tissues." (PMID 29108281, 2017). "To determine, whether Frizzled 8 expression had an impact on stem cell properties, knockdown of Fzd8 was performed in H-Ras cells, which resulted in an increased tumour sphere formation." (PMID 37108193, 2023). "The circular RNA of NEK6 may increase the expression of Frizzled class receptor 8 (FZD8), a constituent of the Wnt signaling pathway, since it binds and inhibits mRNA-370-3p, a tumor suppressor." (PMID 32294979, 2020). "Therefore, we concluded that miR-375 functions as a tumor-suppressive microRNA by directly acting upon FZD8, which may serve as a new therapeutic target to inhibit tumor metastasis in CRC." (PMID 27276676, 2016). "Researchers found that silencing of the WNT-5A receptors Frizzled 8 (FZD8) and RYK attenuated TGF-β-induced ECM expression; future work needs to be done to analyze the expression status of RYK in different tumor stages and its role in progression of LSCC." (PMID 35715770, 2022). "The results showed that the growth factor LR interacts with PDGFB : PDGFRA, IGFBP4:FZD8, and TGFB1:SDC2 with TAMs and tumor vascular cells." (PMID 35664733, 2022). "Tumour cells present in the TME, for example, express FZD8 and LRP5/6 coreceptors known to interact with WNT4 ligand." (PMID 34841720, 2021). "To determine the expression levels of FZD8 in RCC, we performed a quantitative reverse transcription-polymerase chain reaction (qRT-PCR) in 20 pairs of RCC samples and adjacent non-tumor samples." (PMID 29108281, 2017). "The relative mRNA expression levels of FZD8 were found to be increased significantly in the RCC samples (P<0.01), compared with those in the matching adjacent non-tumor tissues." (PMID 29108281, 2017). "In the present study, we examined the expression of FZD8 mRNA and protein in patients with RCC and found it to be upregulated in tumors, compared with non-tumor tissues." (PMID 29108281, 2017).
tumor (continued). "We have previously shown a significantly increased expression levels of FZD8 (one of the Wnt receptors), c-Myc and CSC in residual TNBC tumor after chemotherapy." (PMID 28817737, 2017). "Meanwhile, FZD-8, a receptor of Wnt/β-catenin signaling pathway, was demonstrated a direct target of miR-100, and downregulation of miR-100 increased the migration and invasion of MCF-7 breast cancer cells." (PMID 30563983, 2018). "To further investigate the increased expression of FZD8 in RCC tissues, we performed immunohistochemical staining for FZD8, and detected that FZD8 protein expression was highly increased in RCC samples, compared with matching non-tumor samples." (PMID 29108281, 2017). "In the present study, we examined FZD8 protein expression in clinical human RCC tissues and peri-tumor tissues, as well as the function of FZD8 in RCC cell lines, which will further explain the tumorigenicity of RCC and provide potential therapeutic target for RCC." (PMID 29108281, 2017). "The Fzd8 soluble extracellular domain suppresses Wnt-driven tumor growth in vivo and two sFRPs, FrzA and FrzB inhibited Wnt-1–mediated increase in cytoplasmic β-catenin levels, TCF transcriptional activity in vitro, and tumor growth and metastasis." (PMID 22606268, 2012). "The promoters of DSP, FZD8, KCNH2, and PPP1R14A were methylated in 28%, 67%, 22%, and 78% of the 36 tumor samples, respectively, but not in control samples." (PMID 24260260, 2013).
infection (1 paper, 2021). The state of being infected such as from the introduction of a foreign agent such as serum, vaccine, antigenic substance or organism. "Fzd8 served as a negative control because it did not colocalize with E. chaffeensis during infection and the recombinant protein weakly interacted with TRP120." (PMID 33883266, 2021).
FZD8 also shares sentences with these, for which no sentence is quoted: metastatic cancer (2 papers); osteosarcoma (2); papillary thyroid cancer (2); acute myeloid leukemia (1); allergic asthma (1); atrial fibrillation (1); B-cell lymphoma (1); breast (1); chronic kidney disease (1); esophageal cancer (1); liposarcoma (1); malignant peripheral nerve sheath tumor (1); metastatic tumors (1); microphthalmia (1); myopia (1); osteoarthritis (1); Osteopenia (1); pancreatic adenocarcinoma (1); Retinal coloboma (1); round cell liposarcoma (1); teratocarcinoma (1).